ADARB1 (adenosine deaminase RNA specific B1)
Diseases named in the same sentence as ADARB1 in open-access papers (continued):
Sharing a sentence is not in itself a finding about the gene and the disease.
Obesity (1 paper, 2023). Accumulation of substantial excess body fat. "As ADAR2 overexpression has no adverse effects on motor, lung, or heart functions, except for simple obesity due to chronic hyperphagia in ADARB1 transgenic mice, ADAR2 activity is safely restored by gene therapy." (PMID 37408276, 2023).
ocular infection (1 paper, 2024). "Notably, the top 50 DRE sites (ranked by empirical P-values) in the different tissue types were strongly correlated with ADAR and ADARB1 expression, pointing to an active role of ADARs during ocular infection of SARS-CoV-2." (PMID 38693480, 2024).
prion disease (1 paper, 2020). A transmissible disease that is caused by a protein that is able to induce abnormal folding of normal cellular proteins, leading to characteristic spongiform brain changes, which are associated with neuronal loss without an inflammatory response. "The expression levels of the ADAR enzymes, Adar1 and Adarb2 did not change during prion disease progression, whereas Adarb1 was significantly downregulated at the terminal stage." (PMID 32598380, 2020).
prostate carcinoma (1 paper, 2019). A carcinoma that arises from epithelial cells of the prostate gland. "However, a clustering analysis based on gene function showed that ADARB1 was upregulated in prostate cancer (PCa) tissues." (PMID 31491024, 2019).
sarcoidosis (1 paper, 2023). Sarcoidosis is a multisystemic disorder of unknown cause characterized by the formation of immune granulomas in involved organs. "We found that, unlike their control counterparts, both cardiac and BAL sarcoidosis T cells showed enrichment of memory T cell TF genes (RFX7 and ZEB1), survival and proliferation TF genes (HLF and HIST1H2BN) and type 3 response TF genes (ARNTL and ADARB1)." (PMID 37576111, 2023).
teratoma (1 paper, 2024). A non-seminomatous germ cell tumor characterized by the presence of various tissues which correspond to the different germinal layers (endoderm, mesoderm, and ectoderm). "As expected, ADAR exhibited ubiquitous expression across all teratoma cell-types, while ADARB2 was neural-specific and ADARB1 was most highly expressed in neural tissues, and at lower levels elsewhere." (PMID 39537590, 2024). "Similar to week 10 teratomas, we observed ubiquitous expression of ADAR across all stages of teratoma development, while ADARB2 exhibited neural-specific expression, and ADARB1 showed strongest expression in neural tissues but also was expressed at low levels elsewhere." (PMID 39537590, 2024). "Notably, within Schwann Cell Progenitors (SCPs), ADARB1 (p-value = 4.13E-02, Cohen’s D = 1.73), in comparison to ADAR (p-value = 9.26E-02, Cohen’s D = 1.21), seemed to mostly contribute to the significant rise in SCP AEI (p-value = 1.56E-03, Cohen’s D = 2.01) throughout teratoma development." (PMID 39537590, 2024).
viral pneumonia (1 paper, 2023). Inflammation of the lung parenchyma that is caused by a viral infection. "The RNA editing profiles of most viral pneumonia were similar to those in IBP pneumonia, with Adar up-regulated and Adarb1 down-regulated." (PMID 37081881, 2023).
tumor (17 papers, 2015 to 2025). "We hypothesized that ADARB1 might have a significant effect on immune regulation in OC since it is obviously associated with various types of tumor-infiltrating lymphocytes, immunomodulators, and chemokines in OC." (PMID 35004651, 2021). "Tumor suppression caused by overexpression of adenosine deaminase RNA-specific B1 (ADARB1) is the result of DNA demethylation signal transduction, and inactivation of DNA methylation using a DNA methyltransferase inhibitor significantly enhances ADARB1-mediated metastatic inhibition of LUAD cells." (PMID 36523974, 2022). "Gene expression analysis revealed that ADAR and ADARB1 were significantly upregulated in tumor tissues compared to normal counterparts." (PMID 41300768, 2025). "In silico analyses of TCGA cohorts confirmed differential expression of all three ADAR family members, with ADAR (ADAR1) and ADARB1 (ADAR2) being significantly upregulated in tumor tissues, while ADARB2 (ADAR3) was markedly downregulated." (PMID 41300768, 2025). "Bioinformatics analysis indicated that ADARB1 participated in the mitochondrial respiratory chain and interacted with the tumor–immune system." (PMID 40852728, 2025). "TISIDB and GEPIA databases were further used to analyze the role of ADARB1 in tumor-immune system interactions in GBM." (PMID 35177985, 2022). "RNA editing of SLC22A3 regulated by ADARB1 promotes tumor invasion and metastasis in early familial esophageal carcinoma." (PMID 35004651, 2021). "TISIDB databases were further used to analyze the roles of ADARB1 in tumor-immune system interactions in OC patients." (PMID 35004651, 2021). "Cell proliferation assay and clone formation assay showed that overexpression of ADARB1 (ADARB1-OE) inhibited the proliferation of tumor cells." (PMID 35004651, 2021). "To evaluate changes in ADARB1 expression in LUAD and adjacent non-tumor tissues, we analyzed the transcriptional levels of ADARB1 through seven independent bioinformatics databases." (PMID 31491024, 2019). "Using both tumor and cell line over-expression and knock down experimental data the authors present a compelling case for Adarb1 levels regulating editing in both genes." (PMID 26768488, 2016). "In GBM, ADARB1 has been extensively reported as a tumor suppressor gene." (PMID 35177985, 2022). "Similarly, the results in our study indicated that ADARB1-OE significantly inhibited tumor proliferation and metastasis through down-regulating AKT phosphorylation." (PMID 35004651, 2021). "Although these results suggested that ADARB1 may be related to tumor immunity, clinical research is needed for further study." (PMID 35004651, 2021). "In the present study, we demonstrated that ADARB1 expression was significantly down-regulated in OC tissues and cells, and might act as a tumor suppressor gene." (PMID 35004651, 2021). "Moreover, while ADAR expression was higher in tumor compared to patient-matched normal breast tissues (p = 0.005), an inverse borderline-significant trend was observed for ADARB1 (p = 0.1)." (PMID 26440892, 2015). "In GBM, ADARB1-editing activity has been suggested to have a role in tumor suppression, but dysregulation of different ADARs in GSCs remains largely unknown, and the effects of specific altered editing event(s) that may functionally contribute to brain tumor development have not been identified." (PMID 35133980, 2022). "In addition, ADARB1 expression is related to tumor-infiltrating lymphocytes and immunomodulators." (PMID 35004651, 2021). "Moreover, the expression of ADARB1 in tumor tissues was lower than that in adjacent tissues." (PMID 35004651, 2021). "Further, AGTR1 is also involved in regulating immune chemokines, checkpoints and immune regulatory factors such as PECAM1, ADARB1, SPP1 and ENO1, all of them playing important roles in immune cell regulation, tumor cell proliferation and migration." (PMID 39450258, 2024).
tumor (continued). "We found that the expression level of ADARB1, CXCL12 and TABPB were higher in recurrent tumor tissues, whereas the expression level of B2M was lower in recurrent tumor tissues." (PMID 35177985, 2022). "We verified the expression of ADARB1, ETF1, NRP1, and VPS26A in GBM tumor tissues and normal brain tissues through GEPIA." (PMID 32469390, 2020). "Among them, ADARB1 had a lower expression in tumor tissues (P<0.05), and ETF1 and NRP1 were highly expressed in tumor tissues (P<0.05)." (PMID 32469390, 2020). "We observed significant over-expression of ADAR, ADARB1, DDX5/17/20, DGCR8, DICER1, DROSHA, EIF2C1-4 (AGO1-4), GEMIN4, POLR2A, TARBP2, TNRC6A and XPO5 in tumor tissue compared to adjacent mucosa." (PMID 31510013, 2019). "In GEPIA database, both ADARB1 and BMPR2 were downregulated in tumor samples." (PMID 35570745, 2022). "The mRNA expression of CCBE1 and ADARB1 was significantly upregulated, while the expression of COL11A1 and MUC16 was significantly downregulated in LUAC samples compared with non-tumor samples." (PMID 32707902, 2020). "In contrast with the human samples, ADARB1 and CCBE1 were upregulated and COL11A1 and MUC16 were downregulated in FGF14 overexpressing xenograft tumors, which emphasized the tumor suppressing role of FGF14 in NSCLC." (PMID 32707902, 2020). "The expression levels of ADARB1 (P<0.01), ADRB2 (P<0.05) and ANKRD1 (P<0.05) were significantly down-regulated in stage I LUAD tissues; COL1A1 (P<0.05) and MMP13 (P<0.05) were significantly up-regulated in stage I LUAD tissues compared with adjacent non-tumor tissues." (PMID 28881680, 2017). "Based on TCGA clustering data for ADAR, ADARB1, and ADARB2, fold changes in gene expression between tumor and matched non-cancerous tissues were calculated using median expression values." (PMID 41300768, 2025). "In clinical samples collected from 10 patients with HNSCC, the expression of all analyzed genes (ADAR, ADARB1, and ADARB2) varied between tumor and adjacent non-cancerous tissues." (PMID 41300768, 2025). "Importantly, our validation using paired tumor and adjacent non-cancerous tissues confirmed this downregulation for ADARB2 but not for ADAR or ADARB1, suggesting that ADARB2 may represent the most robust biomarker candidate in this context." (PMID 41300768, 2025).
cancer (12 papers, 2017 to 2025). A tumor composed of atypical neoplastic, often pleomorphic cells that invade other tissues. "Previous studies have revealed that downregulated ADARB1 contributes to cancer progression with several malignancies, and the lower expression levels of ADARB1 have been shown to be associated with poor prognosis of patients in different cancers." (PMID 39163514, 2024). "Elevated ADAR1 expression promotes cancer growth and metastasis, whereas in ADARB1 transgenic mice, elevated ADAR2 expression is associated with simple obesity due to chronic hyperphagia, but apparently normal motor, lung, and heart functions." (PMID 34681616, 2021). "Most reports have linked cancer with reduced ADARB1 expression or activity." (PMID 31491024, 2019). "It is important to highlight that ADARB1 serves as a drug target in various diseases including neurological disorders and cancer." (PMID 39408753, 2024). "Research suggests that according to research, there is a positive correlation between ADARB1 and NK cell expression in cancer, which plays a part in inhibiting the development and metastasis of LUAD." (PMID 39450258, 2024). "Adenosine deaminase RNA-specific B1 (ADARB1) is an RNA-editing enzyme involved in the development of various cancer types, including AML." (PMID 36980682, 2023). "At present, research advancement in the field has revealed the relationship between ADARB1 and cancer." (PMID 31491024, 2019). "For ADARB1, both increased and decreased expressions were observed across cancer types." (PMID 41300768, 2025). "Recently, emerging researches have revealed the relationship between ADARB1 and cancer." (PMID 35004651, 2021). "Recently, studies have demonstrated the key roles of ADARB1 in cancer development." (PMID 35004651, 2021). "Recent studies have indicated the possible role of ADARB1 in the development of cancer." (PMID 31491024, 2019). "ADARB1 might display an anti-cancer role through inhibiting AKT phosphorylation." (PMID 35004651, 2021). "Rencently, Adenosine deaminase RNA-specific B1 (ADARB1), an adenosine-to-inosine (A-to-I) RNA-editing enzyme, has been found to play an essential role in the development of cancer." (PMID 35004651, 2021). "Adenosine deaminase RNA-specific B1 (ADARB1), an adenosine-to-inosine (A-to-I) RNA-editing enzyme, has been found to play an essential role in the development of cancer." (PMID 31491024, 2019). "This is crucial because the data obtained from the TCGA database indicate reduced methylation of the promoter of the gene encoding ADAR and increased methylation in the case of ADARB1 and ADARB2 in cancer tissue compared to non-cancerous tissue." (PMID 41300768, 2025). "Additionally, the gene targets of these miRNAs included several cancer driver genes including ZNF704 (targeted by ten miRNAs), MMP16 (targeted by eight miRNAs), and KCNN3, POU2F1, ADARB1, MPZL1, RUNX1T1, UBE2W, and DYRK1A genes (targeted by seven miRNAs)." (PMID 37685851, 2023).
infection (3 papers, 2021 to 2024). The state of being infected such as from the introduction of a foreign agent such as serum, vaccine, antigenic substance or organism. "ADARB1 knockout induces an antiviral immune response, leading to the suppression of infection." (PMID 35004651, 2021). "Meanwhile, upon infection, ADAR expression decreased in the conjunctiva, whereas ADARB1 expression decreased in the limbus and sclera." (PMID 38693480, 2024). "In addition, some genes in B cells were upregulated in response to infection, including IGHM, JACHAIN, and ADARB1." (PMID 38020713, 2023).
ADARB1 also shares sentences with these, for which no sentence is quoted: bipolar disorder (3 papers); psychiatric disorder (3); Alzheimer disease (1); Ataxia (1); breast carcinoma (1); cardiovascular disease (1); chronic lymphocytic leukemia (1); co-infection (1); dementia (1); Encephalopathy (1); gastric cancer (1); HIV-1 infection (1); neurodevelopmental disorder (1); neurological disorders (1); non-small cell lung carcinoma (1); oligodendroglioma (1); osteoporosis (1); pediatric astrocytoma (1); sarcopenia (1).